SOS1 (SOS Ras/Rac guanine nucleotide exchange factor 1)
Diseases named in the same sentence as SOS1 in open-access papers (continued):
Sharing a sentence is not in itself a finding about the gene and the disease.
tumor (continued). "Particularly, son of sevenless 1 (SOS1) has become a target that gained focus in RAS-driven tumor therapy." (PMID 37221195, 2023). "We investigated the anti-tumor efficacy of two KRAS inhibitors BI-3406 (KRAS::SOS1 inhibitor) and sotorasib (KRAS G12C inhibitor) alone or in combination with MEK1/2 inhibitor trametinib and/or PI3K inhibitor buparlisib in seven PDAC cell lines." (PMID 36139627, 2022). "SOS1 has been shown to play a role in tumor growth in lung ADC35, while FOXO3 acts as a tumor suppressor by regulating apoptosis." (PMID 34117251, 2021). "These proteins included EGFR (a receptor of the EGFR pathway that we found activated in QM-PDAC tumours), SOS1 and GRB2 (both of which are upstream signalling proteins in the canonical MAPK signalling pathway)." (PMID 30018740, 2018). "Chb-M’-mediated down-regulation of SOS1 was also observed in the in vivo samples resected from the tumor, which originated from the xenotransplanted MKN45 cells in immunodeficient NOD/Shi-scid/IL-2Rγnull (NOG) mice." (PMID 29686309, 2018). "Chb-M’ treatment down-regulated the SOS1 protein expression in 7 out of 9 cell lines (77.8%) and significant anti-tumor efficacy was observed in 5 out of 9 cell lines (55.6%)." (PMID 29686309, 2018). "Our study aligns with this hypothesis, as we have observed that the si-SOS1 could replicate the inhibitory effects of miR-152-3p on self-renewal and tumor growth of LCSLC." (PMID 38622665, 2024). "Overall, these observations strongly suggest that the clinical benefit of targeting SOS1 is not limited to only blocking direct tumor growth, but also to reducing the various clinically deleterious effects of different stromal subpopulations of the TME in LUAD." (PMID 37730692, 2023). "Inhibitors of SOS1 may be less sufficient to achieve clinical responses in tumor patients as single agents and, thus, combinations are required to maximize the efficacy and to limit the toxicity against normal tissues." (PMID 36048281, 2022). "These are benign tumor-like lesions consisting of an osteoblast-like cell population, already described in patients with NS or other RAS-opathies, whose higher incidence has been described to be linked to cases due to mutations in SOS1." (PMID 35986401, 2022). "In vivo, subcutaneous tumor formation in BALB/c nude mice revealed that knockdown of SOS1 reduced tumor growth by comparing the size and the weight of tumors in the two groups, K562-NC (negative control) and K562-SOS1-siRNA#3, consistent with the in vitro result." (PMID 34938856, 2021). "These recent observations in keratinocytes confirm and extend previous reports in primary MEFs and in a wide array of tumor cell lines that also demonstrated a preferential role of SOS1 in the control of cell proliferation and activation of the RAS–ERK pathway." (PMID 34205562, 2021). "Furthermore, there were two genes (FBXW7, RET) mutated exclusively in tumours and eight (BLM, GJB2, NOTCH2, NOTCH3, NTRK1, POLE, SOS1, TSC2) solely in metastases." (PMID 34572946, 2021). "In mutant-KRAS tumor cells, inhibition of SOS1 led to a 50% reduction in phospho-ERK." (PMID 34845311, 2021). "Finally, single Sos1 ablation specifically delayed the onset of chemically-induced skin tumor initiation, decreased tumor growth, and prevented malignant progression of papillomas." (PMID 33946974, 2021). "Sos1(pY974) predicted to interact with GRB2 is an unreported novel interaction that we found upregulated in tumor cells might be a novel branch of Erk activation." (PMID 23826330, 2013). "In summary, the data presented in this report strongly indicate that SOS1 functionality is critically required for both the development of the LUAD tumor masses and for the generation of TME alterations that may also play significant pro-tumorigenic roles in LUAD development." (PMID 37730692, 2023). "Next, we asked whether the tumor‐promoting effect of PPDPF in PDAC was SOS1‐dependent." (PMID 36453576, 2023).
tumor (continued). "Downregulation of EPS8, SOS1, or RAC1 in PDAC cells suppresses cell movement but also increases integrin αVβ6-dependent TGFβ activation through Rho activation, which has both tumor suppressing and activating effects." (PMID 39354505, 2024). "Our findings show that SOS1 and MEK inhibitors (SOS1i+MEKi) suppressed tumor growth in syngeneic models and increased intratumoral CD8+ T cells without durable responses." (PMID 38727236, 2024). "In our nude mouse graft model, the knockdown of DNMT1 led to the inhibition of tumor growth, accompanied by decreased protein expression of DNMT1, SOS1, and CD44 and increased levels of miR-152-3p." (PMID 38622665, 2024). "Although the structure has not been reported, BI-1701963 was selected as a clinical-stage inhibitor of the SOS1:KRAS PPI, and has displayed tumor regressions in several tumor models in mice when dosed in combination with a KRASG12C inhibitor." (PMID 37108538, 2023). "Functionally, SOS1R1, SOS1R2 and SOS1R1/R2 had little effect on tumor cell growth in vitro and in vivo in SOS1 knockout HPAC cells, while SOS1 WT showed a strong growth‐promoting effect." (PMID 36453576, 2023). "Chemically altered MIR143 considerably inhibits tumor growth by affecting AKT, KRAS, extracellular signal-regulated kinases (ERK), and son of sevenless homolog 1 (SOS1)." (PMID 37371705, 2023). "Furthermore, three CML Supertarget genes, that is, GRB2-associated binding protein 2 (GAB2), son of sevenless homolog 1 (SOS1), and signal transducer and activator of transcription 5B (STAT5B), are the components of JAK/STAT signaling pathway critical in BCR-ABL1-positive neoplasms." (PMID 37297004, 2023). "The search for inhibitors of SOS1 has yielded four compounds so far, namely BAY-293, MRTX0902, BI-3406 and BI-1701963, that inhibit KRAS-dependent tumor growth in vitro and in xenograft models." (PMID 36048281, 2022). "Pre-clinical models showed that the combination of the SOS1:KRAS and MEK inhibition resulted in tumor regression." (PMID 34845311, 2021). "Therefore, miR-143#12, which extremely silenced K-RAS and its effector-signaling molecules Akt and Erk, as well as SOS1, could induce a potent anti-tumor effect with apoptosis in K-RAS-dominant 253J-BV BC cells, which reflected the induction of apoptosis in the case of K-RAS mutant T24 BC cells." (PMID 30911586, 2019). "EGFR and SOS1 levels were found to be higher in the p-AKTHIGH, Bcl-2LOW HepG2-transplanted tumor than in the wild type HepG2 tumor." (PMID 25980493, 2015). "TGFBR2, SMAD3, SMAD5, SOS1 and SOS2 were found to be lower expressed in VEGFA165 tumours compared with control tumours." (PMID 22045186, 2011). "Notable, genes involved in TGF-β signalling (SOS1, SOS2, SMAD5, LTBP3, TGFBR2, IRF7 and CREBZF) were found to be significantly (P<0.01) downregulated in the VEGFA165 tumours." (PMID 22045186, 2011). "Importantly, SIAIS562055-mediated SOS1 degradation overcame acquired resistance to KRAS inhibitors, leading to tumor regression in mouse xenograft models when combined with KRAS inhibitors." (PMID 39437162, 2025). "Furthermore, in MIA PaCa-2/R tumor tissues, the co-administration of SIAIS562055 with MRTX849 resulted in significant degradation of SOS1, leading to a more pronounced reduction of ERK phosphorylation and enhanced cleavage of caspase-3." (PMID 39437162, 2025). "SOS1 has a dominant role in GDP-GTP exchange and due to its unique participation in the negative feedback loop of the KRAS pathway, it has been recognized as a significant tumor target." (PMID 40244134, 2025). "Grb2 SUMOylation recruits Sos1 (son of sevenless homolog 1) for the formation of Grb2-Sos1 results in the initiation of signaling pathway RAS/MEK/MAPK that consequently plays pivotal roles in carcinogenesis, cell migration, and tumor development." (PMID 38590645, 2024). "We aimed to demonstrate that the DNMT1/miR-152-3p negative pathway upregulates SOS1 expression in NSCLCs to induce self-renewal and tumor growth in CSLCs." (PMID 38622665, 2024).
tumor (continued). "The critical requirement of SOS1 for KRASG12D-driven LUAD is further confirmed by means of intravenous tail injection of KRASG12D tumor cells into SOS1KO/KRASWT mice, or of SOS1-less, KRASG12D tumor cells into wildtype mice." (PMID 37730692, 2023). "Of note, the SOS1 DepMap dependency score calculated here for human LUAD cell lines appears to be clearly lower than the one previously reported for human CML cell lines, another tumor type where SOS1 is also critically required for malignant development." (PMID 37730692, 2023). "SOS1 is a guanine nucleotide exchange protein, and exerts indispensable role in the activation of RAS protein, which then stimulates the downstream pathways including the MEK/ERK pathway and PI3K/AKT pathway to facilitate tumor cell survival." (PMID 37626035, 2023). "These differential affinities of KRAS mutants for SOS1 might have important implications in tumours, as KRAS binds to SOS1 in the enzymatic pocket but can also regulate its function by binding to an allosteric regulatory pocket." (PMID 37627169, 2023). "Such enhancers can be targeted by bromodomain and extra-terminal (BET) inhibitors (BETi) or degraders and this review discusses whether integrated SOS1 inhibition and BET targeting of MYC synergizes against mutant KRAS tumor growth." (PMID 38023987, 2023). "Bioinformatic analyses predicted that APEX1 might interact with cell division cycle 42 (CDC42) and son of sevenless homolog 1 (SOS1), which are involved in tumor metastasis." (PMID 33946672, 2021). "In this study using bioinformatic technology, we found that IL-6R, SOS-1, NF-IL-6, c-Fos, MAP3K10, NIK, SP1, MEF2, and other inflammatory factors and tumor regulatory molecules are also potential target genes of miRNA-155, but no definitive results have been reported yet." (PMID 27462776, 2016). "The downregulated antigens T11-5, T5-13 (Sos1), and T5-15 do not react with sera from patients B82-B96 analyzed for tumor mRNA expression." (PMID 15541172, 2004). "Furthermore, the effects of SIAIS562055 on SOS1 degradation and pERK inhibition in MIA PaCa-2 tumor tissues correlated with the in vitro results, as confirmed by the significant suppression of SOS1/KRAS/ERK signaling and induction of caspase-3 cleavage upon treatment with SIAIS562055." (PMID 39437162, 2025). "In yeast, FBP binds to the H-RAS/SOS1 complex, a guanine nucleotide exchange factor (GEF), promoting RAS-GTP activation and enhancing oncogenic signaling, which suggests that increased glycolytic flux may amplify tumor-promoting pathways." (PMID 40734168, 2025). "Therefore, it is reasonable to infer that the DNMT1/miR-152-3p negative feedback loop critically sustains self-renewal and tumor growth of LCSLC through SOS1." (PMID 38622665, 2024). "Furthermore, miR-152-3p may upregulate SOS1 by activating DNMT1, thereby promoting self-renewal and tumor growth in LCSLCs." (PMID 38622665, 2024). "Previous studies showed that E5 does not promote any changes in ERK activity in cultured fibroblasts as well as in BPV-induced tumours in vivo: it is therefore possible that pPDGFβR activates GRB2, Sos1, and Ras which may deviate on phosphatidylinositol-3-kinase/AKT pathway (PI3 K/AKT)." (PMID 23936786, 2013). "The presence or absence of the EPS8/SOS1/ABI1 complex acts as a molecular switch in PDAC cells to balance RAC1 and RhoA activation to promote tumor migration or TGFβ activation, respectively." (PMID 39354505, 2024). "Strikingly, our results showed that the absence of SOS1, but not SOS2, in the lungs of the recipient, injected mice dramatically reduced the tumor burden of KPB6-dependent lung tumors as compared to their SOS1/2WT/KRASWT WT counterparts." (PMID 37730692, 2023). "In the present study, we found that both human HCC tumor foci and the selected TRCs were among the high expressors for SOS2, but not for SOS1, which remained low and unchanged." (PMID 34479623, 2021).
tumor (continued). "Importantly, unlike KRAS mutant-specific inhibitors, SOS1 inhibition and MEK inhibition in our study is not limited to targeting KRAS pathway only in tumor cells." (PMID 38727236, 2024). "In addition, targeting the SOS-1-KRAS interaction, due to the functional compensation of its paralog SOS-2 and the lack of requirement in normal versus tumor cells, might also be less toxic." (PMID 40141222, 2025). "Since none of members in SOS1/EPS8/ABI1 tri-complex is dispensable in the Rac activation, and ABI1 acts as a scaffold protein, we hypothesize that ABI1 may be an ideal target to design anti-tumor drugs." (PMID 31488087, 2019).
infection (25 papers, 2011 to 2026). The state of being infected such as from the introduction of a foreign agent such as serum, vaccine, antigenic substance or organism. "The function of the potato SOS1 gene (StSOS1-13) responding to the FOX infection was researched by gain- and loss-of-function assays." (PMID 40115954, 2025). "However, since tamoxifen appears to affect the viability of keratinocytes in culture even at low concentrations, we decided to test the efficiency of GFP-Adeno-Cre infection as an alternative method to accomplish Sos1 depletion in freshly isolated Sos1 KO and Sos1/2 KO primary keratinocytes." (PMID 33946974, 2021). "We employed real-time PCR to detect 40 GAP and GEF genes and determined that the mRNA levels of SOS1, RasGRP3, Ect2, and Collybistin were increased in HepG2 cells after rAd-ASPP2 infection for 48 and 72 hours." (PMID 25980493, 2015).
heart disease (3 papers, 2020 to 2025). "Among patients with SOS1 variants, 90% presented heart disease, with PS being the most prevalent (66%), while HCM was present in 17% of cases." (PMID 40332000, 2025).
metabolic disorder (2 papers, 2018 to 2019). "The data suggest that aging subjects develop cardiac abnormalities due to metabolic disorders in numerous metabolites as well as alterations in gene expressions, such as SOS1, CREB, IRS1, GRB2 and GSK3β." (PMID 30669571, 2019). "Cardiac abnormality by PM2.5 exposure might due to metabolic disorder in numerous metabolites as well as alteration in gene expression such as SOS1, CREB and GSK3b." (PMID 30112104, 2018).
adenocarcinoma (1 paper, 2021). A common cancer characterized by the presence of malignant glandular cells. "For example, in our cohort, canonical oncodriver mutations were identified in three of the six tumors with an adenocarcinoma component (SOS1 in Pa34, EGFR/PIK3CA in Pa35, and KRAS/PIK3CA in Pa37) compared to pure LUADs, the majority of which harbor driver mutations." (PMID 34873156, 2021).
blood cancers (1 paper, 2021). "Since some AML cell lines harbor SOS1 mutations and are dependent on SOS1 for survival, a combination of SOS1 and MEK inhibitors may be an attractive strategy for the treatment of blood cancers containing KRAS mutations." (PMID 33801965, 2021).
SOS1 also shares sentences with these, for which no sentence is quoted: cardiofaciocutaneous syndrome (6 papers); pancreatic ductal adenocarcinoma (4); lymphedema (3); acute myeloid leukemia (2); breast tumor (2); cardiac hypertrophy (2); fibrosarcoma (2); Lymphatic Disorder (2); schwannomatosis (2); Splenomegaly (2); ventricular septal defect (2); alcoholism (1); Anaplastic Thyroid Carcinoma (1); aortic stenosis (1); atrioventricular septal defect (1); autoimmune disorder (1); Bardet-Biedl syndrome (1); bile duct cancer (1); brain disease (1); cardiomyopathy (1); cartilage disease (1); CHARGE syndrome (1); cocaine addiction (1); Cognitive impairment (1); colon adenocarcinoma (1); congenital heart disease (1); Cornelia de Lange syndrome (1); COVID-19 (1); Cowden syndrome (1); Cutis verticis gyrata (1).
A further 56 diseases each share a sentence with SOS1 in 1 paper.